RFLNA (refilin A)
Description:
Involved in the regulation of the perinuclear actin network and nuclear shape through interaction with filamins. Plays an essential role in actin cytoskeleton formation in developing cartilaginous cells.
Synonyms: RefilinA; FAM101A; FLJ44614; Cfm2; ZNF664-RFLNA
Tractability: No criterion of Open Targets' tractability assessment is met for any kind of drug.
Gene: Protein-coding gene on chromosome 12 (123,973,241 to 124,316,024, forward strand). Ensembl gene ENSG00000178882.
Subcellular location: Cytoplasm, cytoskeleton
Subcellular location (Human Protein Atlas): Focal adhesion sites
Gene Ontology:
Molecular function: protein binding; filamin binding
Biological process: actin filament bundle organization; negative regulation of bone mineralization involved in bone maturation; negative regulation of chondrocyte development; skeletal system morphogenesis; regulation of chondrocyte development
Cellular component: actin filament bundle; cytoskeleton
Genetic constraint (gnomAD): Loss-of-function variants: 5 observed, 4.98 expected, observed/expected ratio (o/e) 1, 90% interval 0.51 to 1.81. That is too few expected variants to judge how well the gene tolerates losing a copy. Missense variants: 235 observed, 245.64 expected, observed/expected ratio (o/e) 0.96, 90% interval 0.86 to 1.07. Synonymous variants: 119 observed, 107.62 expected, observed/expected ratio (o/e) 1.11, 90% interval 0.95 to 1.29.
Homologues: Orthologues: chimpanzee RFLNA (98% identical), macaque RFLNA (98% identical), pig RFLNA (88% identical), rat Rflna (73% identical), mouse Rflna (70% identical), dog RFLNA (67% identical), tropical clawed frog rflna (62% identical), zebrafish rflna (55% identical). Paralogues in human: RFLNB (24% identical).
Diseases named in the same sentence as RFLNA in open-access papers:
RFLNA is named in the same sentence as 7 diseases in open-access papers, as found by Europe PMC text mining. Sharing a sentence is not in itself a finding about the gene and the disease. The quoted sentences say what the papers report.
Spondylocarpotarsal synostosis (2 papers, 2019 to 2025). "To date, there is only limited evidence for disease associations of DAO (schizophrenia), RFLNA (spondylocarpotarsal synostosis), and EHHADH (Fanconi renotubular syndrome)." (PMID 31533369, 2019). "Recently, a homozygous mutation in RFLNA was found in a patient suffering from spondylocarpotarsal synostosis syndrome, a rare syndromic skeletal disorder characterized by disrupted vertebral segmentation with vertebral fusion, carpal and tarsal synostosis, but also with scoliosis and short stature." (PMID 31533369, 2019).
RFLNA also shares sentences with these, for which no sentence is quoted: spondylocarpotarsal synostosis syndrome (2 papers); Fanconi renotubular syndrome (1); hepatocellular carcinoma (1); Insulin resistance (1); schizophrenia (1); scoliosis (1).